LOXL3 (lysyl oxidase like 3)
Diseases named in the same sentence as LOXL3 in open-access papers (continued):
Sharing a sentence is not in itself a finding about the gene and the disease.
melanoma (continued). "On the contrary, LOX and especially LOXL2, LOXL3, and LOXL4 were found to be upregulated in several human melanoma cell lines, and LOX inhibitor B-aminopropionitrile inhibited the invasive growth of these cells particularly when co-cultured with fibroblasts in Matrigel." (PMID 30701028, 2018). "Since LOXL3-depleted melanoma cells ultimately die after shRNA transduction, we analyzed how A375P cells were able to enter and exit mitosis in the absence of LOXL3 at early time points after infection." (PMID 29229995, 2018). "We then analyzed the cell-cycle progression of melanoma cells and unveiled a consistent accumulation of cells in G2/M phase in the absence of LOXL3 compared to control cells." (PMID 29229995, 2018). "Moreover, confocal microscopy analyses determined LOXL3 and BRCA2 co-localization in the cytoplasm and perinuclear area of melanoma cells." (PMID 29229995, 2018). "However, Loxl3 silencing did not induce cell apoptosis, as is the case in human melanoma cells, but promoted DNA damage, determined by the accumulation of γH2AX and 53BP1 foci in Loxl3-depleted MeL3 cells compared to control cells." (PMID 35267510, 2022). "Thus, enhanced LOXL3 expression cooperates with oncogenic alterations such as active BRAF to transform human melanocytes favoring migration and invasion of melanoma cells and supporting melanoma tumorigenicity." (PMID 29229995, 2018). "We have exposed a novel LOXL3–SNAIL1–PRRX1 axis relevant to melanoma phenotype switching, the targeting of which might represent an opportunity to combat resistance to targeted and immune-based therapies, a remaining challenge in the clinical management of melanoma." (PMID 35267510, 2022).
breast carcinoma (12 papers, 2017 to 2025). "Additional research is warranted to clarify the association between LOXL3 and breast cancer, as well as its fundamental mechanisms." (PMID 39247609, 2024). "Tnc, Col8a1, Loxl3 and Plau), several of which have been shown to support cancer cell invasion and associate with poor clinical outcome in breast cancer patients." (PMID 38849373, 2024). "Studies have shown that the expression levels of LOXL1, LOXL2, and LOXL3 are elevated in breast cancer tissues compared to normal tissues." (PMID 41250755, 2025). "Subsequent analysis of a clinical tissue microarray (TMA) comprising 368 invasive breast cancer samples has revealed cytoplasmic expression of LOXL3 in approximately 26.0% (76/292) of breast cancer patients." (PMID 39247609, 2024). "Limited research has been conducted on the function and mechanism of LOXL3 protein in breast cancer." (PMID 39247609, 2024). "It has been shown that breast cancer becomes more invasive upon increased collagen bundling, with invasion of ductal breast cancer cells into collagen matrices mediated by lysyl oxidase-like 3 that reinforces local matrix stiffness." (PMID 36765749, 2023). "In short, we find that LOXL3 is upregulated in collectively invading ductal-type breast cancer organoids in cells that are in contact with collagen matrices and at the invasive front in IDC-NST." (PMID 35292774, 2022). "Associations of LOXL3 expression with EMT (through E-cadherin transcription repression by SNAIL), cell invasion in breast cancer, and with GBM cell adhesion and invasion have been described." (PMID 36076905, 2022). "Based on these findings, we conclude that collective invasion of ductal-type breast cancer in Collagen-I-dense matrices can be promoted by Loxl3." (PMID 35292774, 2022). "Collective invasion into collagen matrices by ductal breast cancer cells depends on Lysyl oxidase-like 3 (Loxl3), a factor produced by tumor cells that reinforces local collagen stiffness." (PMID 35292774, 2022). "We examined expression of LOXL3 in the cytoplasm and find detectable expression in 76/292 (26.0%) of breast cancer cases." (PMID 35292774, 2022). "In conclusion, we find that collectively invading ductal-type breast cancer cells depend on collagen remodeling in part by Loxl3." (PMID 35292774, 2022). "Our work shows that Loxl3 expression by basal-type cells at the invasive front of ductal type breast cancer promotes collective invasion." (PMID 35292774, 2022). "In a recent study, LOX, LOXL1, LOXL2, and LOXL3 expressions were evaluated by immunohistochemistry in 291 cases of breast cancer." (PMID 31340433, 2019). "As such, we hypothesize that collective invasion of ductal breast cancer depends on an instigating pulse of Loxl3 upon local collagen fiber alignment, followed by crosslinking and bundling of collagen fibers." (PMID 35292774, 2022). "Overall, we speculate that while the impact of LOXL3 inhibition may vary with breast cancer subtype, the specific therapeutical inhibition of both LOXL1 and LOXL2 but not of LOXL4 may be beneficial in breast cancer." (PMID 35800439, 2022). "We speculate that while the impact of LOXL3 inhibition may vary with breast cancer subtype, the therapeutical inhibition of LOX, LOXL1 and LOXL2 but not of LOXL4 may be the most beneficial." (PMID 35800439, 2022). "LOXL3 expression was detected in breast cancer, both in primary and pleural effusion." (PMID 31340433, 2019). "However, there are few studies on the role of LOXL3 in breast cancer." (PMID 39247609, 2024). "Therefore, we speculate that LOXL3 may play a role in promoting breast cancer." (PMID 39247609, 2024). "Our data suggest that Loxl3 expression by basal leader cells induces local ECM stiffening, thereby enabling collective invasion of ductal-type breast cancer." (PMID 35292774, 2022).
breast carcinoma (continued). "Further analysis of data derived from the GSE9014 set 35 showed that the expression of LOXL4, but not LOXL3, was significantly higher in breast cancer samples than in normal breast samples." (PMID 32754259, 2020). "This temporal and spatial/regional regulation of ECM stiffness by invading tumor cells may be responsible for the lack of correlations between LOXL3, clinicopathological parameters, and breast cancer subtypes in our TMA cohorts." (PMID 35292774, 2022).
glioma (11 papers, 2018 to 2025). A benign or malignant brain and spinal cord tumor that arises from glial cells (astrocytes, oligodendrocytes, ependymal cells). "Further investigation into the relationship between LOXL3 and the Wnt/β-catenin signaling pathway in glioma will help elucidate the underlying mechanisms of gliomagenesis and provide new targets and insights for developing more effective therapeutic strategies." (PMID 41250755, 2025). "Additionally, both LOXL1 and LOXL3 in glioma are implicated in the Wnt/β-catenin signaling pathway, and this signaling pathway plays an important role in regulating cell migration and apoptosis." (PMID 41250755, 2025). "Generally, in glioma, LOXL3 is highly expressed, and its elevated expression is associated with poor prognosis." (PMID 41250755, 2025). "Apart from glioma, our data revealed the role of LOXL3 overexpression in macrophages and in predicting the response to immune checkpoint blockade in bladder and renal cancers." (PMID 40186284, 2025). "The experimental results in our present work demonstrated the elevations of LOX, LOXL1, LOXL2, and LOXL3 in various glioma cell lines." (PMID 36160460, 2022). "Experimental results revealed that expressions of LOX, LOXL1, LOXL2, and LOXL3 were higher in glioma cell lines at mRNA and protein levels." (PMID 36160460, 2022). "T98G glioma cell line was also silenced for LOXL3 with siRNA1, with efficacy confirmed by RNA expression and protein analysis 4 days after transfection." (PMID 34360836, 2021). "In glioma, LOXL3-driven ECM remodeling may create a favorable microenvironment for the activation of the Wnt/β-catenin signaling pathway, thereby promoting tumor cell proliferation and invasion." (PMID 41250755, 2025). "Low Loxl3 decreased glioma invasion and restrained tumor progression." (PMID 38978755, 2024). "Additionally, experimental results also revealed that expressions of LOX, LOXL1, LOXL2, and LOXL3 were higher in glioma cell lines (T98G and A172) at mRNA and protein levels compared with the normal astrocyte HEB." (PMID 36160460, 2022). "The results indicated that the mRNA and protein expressions of LOX, LOXL1, LOXL2, and LOXL3 were significantly upregulated in these glioma cells than in HEB cell line while the expressions of LOXL4 at mRNA and protein level were not determined in these cell lines (data not shown)." (PMID 36160460, 2022). "The results indicated that members of the LOX family, including LOX, LOXL1, LOXL2, LOXL3, and LOXL4, exhibited high expression levels in glioma cells in comparison to normal human glial cell lines Heb as well as glioblastoma cell lines T98G and LN-229." (PMID 40270974, 2025). "Loxl3 can promote tumor cell invasion in GBM, and Loxl4 is recognized as a stemness-related prognostic biomarker in glioma." (PMID 38978755, 2024). "LOXL2 and LOXL3, members of the lysyl oxidase (LOX) family, LOXL2 was found to promote glioma progression, and improve the TMZ resistance of glioma cells." (PMID 36856182, 2023). "The cell lines derived from gliomas (U138MG and U87MG) were in the top five cell lines presenting the highest LOXL3 expression levels among the 64 human cell lines of the HPA study." (PMID 34360836, 2021). "The results shown in CGGA-325 dataset revealed that the glioma patients with the high levels of all members of LOX family including LOX, LOXL1, LOXL2, LOXL3, and LOXL4 displayed poor prognosis with the MST of only 34.3, 31, 31, 35.3, and 34.8 months, respectively." (PMID 36160460, 2022). "Finally, RT-qPCR and Western blot analysis were carried out to validate the mRNA and protein levels of LOXs including LOX, LOXL1, LOXL2, LOXL3, and LOXL4 in glioma cells (T98G and A172) and the normal cell line (HEB)." (PMID 36160460, 2022).
glioma (continued). "In the present study, a progressive increase in levels of LOX, LOXL1, and LOXL3 expression was observed for LGG-IDHmut, LGG-IDHwt, and GBM in the TCGA glioma RNAseq dataset, suggesting their role in determining ECM composition and stiffness enhancement in these phenotypes." (PMID 36076905, 2022). "Regarding the roles of LOXL1-4 in the glioma, LOXL1 is also demonstrated to exhibit antiapoptotic activity and promote glioma cell proliferation while the facilitation of cell invasion for LOXL3 is observed in glioma cell line U87MG." (PMID 36160460, 2022). "Therefore, we analyzed the contribution of LOXL3 to the pathogenesis and aggressiveness of GBM through in silico analysis and cellular assays using the U87MG glioma cell line as a model system." (PMID 34360836, 2021).
myopia (8 papers, 2015 to 2025). "Early-onset severe myopia was associated with homozygous null mutation on LOXL3 (c.39dup, p.Leu14Alafs*21) and heterozygous combination of this mutation with another frameshift mutation (c.594delG, p.Gln199Lysfs*35)." (PMID 31340433, 2019). "Patients with the missense variant in human LOXL3 gene, which is believed to cause autosomal recessive Stickler syndrome, exhibit conditions of micro/retrognathia, cleft palate, myopia and mild conductive hearing loss." (PMID 26307084, 2015). "Previous studies have indicated that LOXL3 encodes lysyl oxidase-like protein 3, which is responsible for the crosslinking of collagen and elastin, potentially affecting scleral stability and associating with non-syndromic early-onset high myopia." (PMID 41259386, 2025). "Loss-of-function LOXL3 variants have also been associated with early-onset myopia." (PMID 35885918, 2022). "Interestingly, we report a truncating variant in LOXL3 [NM_032603.4:c.824dup;p.(Ala277Cysfs∗57)] in a patient with high myopia, retinal detachment with mild ID (IQ 62)." (PMID 33456446, 2020). "However, more recently, a homozygous missense variant in LOXL3 (c.2027G>A, p.Cys676Tyr) was identified in a family with two affected siblings, presenting micrognathia, cleft palate, and severe myopia." (PMID 31340433, 2019). "Additionally, a family with SS phenotype was reported as harboring a homozygous novel LOXL3 mutation (c.1036C>T, p.Arg346Trp), in which two affected members, the father and a child, presented myopia and retinopathy." (PMID 31340433, 2019). "For non-syndromic genes (P4HA2, LOXL3), milder phenotypes may reflect early myopia progression, which could worsen with age or environmental triggers." (PMID 41259386, 2025). "High myopia is near-universal, and sensorineural hearing loss is very common in patients with variants in genes for type IX or XI collagen, although hearing appears spared in the LRP2 and LOXL3 patients and is variable in GZF1." (PMID 35885918, 2022). "LOXL3 was reported in patients with high myopia and in Sticklers syndrome." (PMID 33456446, 2020). "Patients with Stickler syndrome caused by human LOXL3 mutation present with symptoms of high non-progressive myopia." (PMID 26307084, 2015). "Interestingly, the features of Loxl3 deficient mouse models overlap with a human collagenopathy, called Stickler syndrome, an autosomal dominant disease caused most frequently by COL2A1 and COL11A1 mutations, characterized by high myopia and cleft palate." (PMID 31340433, 2019). "Human LOXL3 presents differential tissue expression regarding other LOX proteins and has been recently proposed as a candidate gene responsible for recessive autosomal Stickler syndrome, a collagenopathy, whereas null mutations in LOXL3 have been associated with early-onset high myopia." (PMID 29229995, 2018).
collagenopathy (7 papers, 2018 to 2025). "Stickler syndrome is a collagenopathy caused by a mutation in the LOXL3 gene with a distinct cleft palate." (PMID 40429955, 2025). "LOXL3, known for its function as a lysyl oxidase, has been associated with embryonic development and diverse pathologies, including collagenopathies and fibrosis." (PMID 34360836, 2021). "Lysyl oxidase-like 3 is known to cross-link type II collagen, which underlines the fundamental collagenopathy in Stickler syndrome." (PMID 30568244, 2019). "LOXL3 is involved not only in embryonic development but also in the pathogenesis of various diseases such as collagenopathies and cancers, collectively underscoring its significance as a potential therapeutic target." (PMID 41250755, 2025). "Interestingly, LOXL3 plays roles in embryonic development and in the pathogenesis of several diseases, including collagenopathies, fibrosis, and cancer, which highlights LOXL3 as a potential target for therapy." (PMID 31340433, 2019).
Stickler syndrome (7 papers, 2015 to 2025). Stickler syndrome is an inherited vitreoretinopathy characterized by the association of ocular signs with more or less complete forms of Pierre-Robin sequence, bone disorders, and sensorineural deafness (10% of cases). "Studies have shown that cleft palate is a prominent phenotype of Stickler syndrome, and LOXL3 mutation can cause Stickler syndrome." (PMID 40429955, 2025). "Biallelic missense variant of LOXL3 was found in Stickler syndrome with mild conductive hearing loss." (PMID 34150778, 2021). "Apart from mutations in genes encoding collagen, a homozygous missense variant in LOXL3 (c.2027G>A, p.Cys676Tyr) was found in two siblings with an autosomal recessive Stickler syndrome, one of the siblings exhibited mild conductive hearing loss." (PMID 34150778, 2021). "To date, mutations in seven genes (COL2A1, COL11A1, COL11A2, COL9A1, COL9A2, COL9A3, and LOXL3) have been reported to cause Stickler syndrome." (PMID 32756486, 2020). "Biallelic LOXL3 mutations have also been linked to a Stickler syndrome phenotype." (PMID 36140739, 2022). "In conclusion, we have demonstrated that Loxl3 plays an essential role in the maintenance of the inner ear function; the results may provide more explanation for the pathology of Stickler syndrome caused by homozygous mutations in LOXL3." (PMID 34150778, 2021). "Except for Stickler syndrome, as a candidate human disease gene, mutations in LOXL3 may also be screened in other patients with cleft palate or spinal deformity." (PMID 26307084, 2015). "Lysyl oxidase-like 3 (LOXL3), a member of the lysyl oxidase family responsible for the crosslinking in collagen, is also one of the mutated genes detected in Stickler syndrome." (PMID 40429955, 2025). "Of the non-collagen genes, LOXL3 mutations seem to mimic the classic Stickler syndrome phenotype most, which might be due to the function of the gene." (PMID 36140739, 2022).
gastric cancer (6 papers, 2019 to 2025). A primary or metastatic malignant neoplasm involving the stomach. "In summary, LOXL3 expression is upregulated in gastric cancer cells and tissues, and its high expression is associated with poor prognosis." (PMID 41250755, 2025). "Functionally, the activation of LOXL3 plays a central driving role in the malignant progression of gastric cancer, not only enhancing the metastatic capacity of cancer cells but also promoting the formation of an invasive phenotype." (PMID 41250755, 2025). "Knockdown of LOXL3 induces ferroptosis in gastric cancer cells, and the specific ferroptosis inhibitor Fer-1 effectively reverses the suppressive effects of LOXL3 knockdown on proliferation, metastasis, and angiogenesis." (PMID 41250755, 2025). "In stomach cancer tissues and cells, signs of increased regulation of LOXL3 expression can be observed (Chu, Huang & Pan, 2025)." (PMID 41250755, 2025). "Inhibition of LOXL3 can trigger iron death in gastric cancer cells, and the specific iron death inhibitor Ferrostatin-1 (Fer-1) effectively eliminates the inhibitory effect of LOXL3 on the proliferation, metastasis, and angiogenesis of gastric cancer cells." (PMID 41250755, 2025). "Transforming growth factor-β (TGF-β) signaling upregulates the transcriptional level of LOXL3 in gastric cancer cells." (PMID 41250755, 2025). "Knockout LOXL3 can be used as an important step in triggering iron death and inhibiting aggressive progression of stomach cancer (Chu, Huang & Pan, 2025)." (PMID 41250755, 2025). "Additionally, this study describes TGF-induced LOXL3 upregulation in gastric cancer cells, suggesting that LOXL3 is downstream from the TGF-signaling pathway." (PMID 40906383, 2025). "Additionally, TGF-induced LOXL3 upregulation in gastric cancer cells suggested that LOXL3 was downstream from the TGF-signaling pathway." (PMID 35433829, 2022). "It was also shown that higher expression of LOXL3 was regulated by TGF-β in gastric cancer." (PMID 35311155, 2022). "Moreover, TGF-β induced LOXL3 upregulation in gastric cancer cells, suggesting that LOXL3 was downstream from the TGF-β signaling pathway." (PMID 31340433, 2019). "Several studies have reported changes in LOX, LOXL1, LOXL2, LOXL3, and LOXL4 expression in gastric cancer." (PMID 40906383, 2025). "Studies have reported that the expression of LOX family members LOXL1, LOXL3, and LOXL4 is related to distant metastasis of gastric cancer." (PMID 34595188, 2021). "In a cohort study involving 597 patients treated with primary treatment for gastric cancer, the OS with positive expression of LOXL1, LOXL3, or LOXL4 was significantly shorter than with negative LOXL4 expression." (PMID 41250755, 2025).